SLC50A1 (solute carrier family 50 member 1)
Description:
Mediates sugar transport across membranes. May stimulate V(D)J recombination by the activation of RAG1.
Synonyms: HsSWEET1; RAG1AP1; SCP; RP11-540D14.5; slv; RZPDo834D038D; SWEET1
Tractability: Antibody: UniProt places it where antibodies can reach, with high confidence; its Gene Ontology location is reachable by antibodies, with high confidence; UniProt predicts a signal peptide or a membrane-spanning region.
Gene: Protein-coding gene on chromosome 1 (155,135,344 to 155,138,857, forward strand). Ensembl gene ENSG00000169241.
Subcellular location: Golgi apparatus membrane; Cell membrane
Pathways (Reactome):
Transport of small molecules: Cellular hexose transport
Gene Ontology:
Molecular function: glucoside transmembrane transporter activity; protein binding; sugar transmembrane transporter activity
Biological process: hexose transmembrane transport; glucoside transport
Cellular component: Golgi apparatus; plasma membrane; endomembrane system; Golgi membrane; membrane
Genetic constraint (gnomAD): Loss-of-function variants: 22 observed, 29.32 expected, observed/expected ratio (o/e) 0.75, 90% interval 0.54 to 1.07. The upper end of that interval is the gene's LOEUF score, 1.07, which puts it in group 4 of 6, group 1 being the genes least tolerant of losing a copy. Missense variants: 233 observed, 288.29 expected, observed/expected ratio (o/e) 0.81, 90% interval 0.73 to 0.9. Synonymous variants: 96 observed, 118.49 expected, observed/expected ratio (o/e) 0.81, 90% interval 0.69 to 0.96.
Homologues: Orthologues: chimpanzee SLC50A1 (100% identical), macaque SLC50A1 (99% identical), guinea pig SLC50A1 (83% identical), dog SLC50A1 (81% identical), mouse Slc50a1 (80% identical), pig SLC50A1 (78% identical), rat Slc50a1 (74% identical), rat Slc50a1-ps1 (58% identical), zebrafish slc50a1 (56% identical), tropical clawed frog slc50a1 (43% identical), Drosophila melanogaster slv (28% identical), Caenorhabditis elegans swt-3 (27% identical), and 6 more.
Diseases named in the same sentence as SLC50A1 in open-access papers:
SLC50A1 is named in the same sentence as 7 diseases in open-access papers, as found by Europe PMC text mining. Sharing a sentence is not in itself a finding about the gene and the disease. The quoted sentences say what the papers report.
hepatocellular carcinoma (1 paper, 2024). A malignant tumor that arises from hepatocytes. "This suggests that SLC50A1 overexpression stimulates rapid proliferation of hepatocellular carcinoma cells." (PMID 39695152, 2024). "Biochemical analyses indicated that downregulation of SLC50A1 expression led to a simultaneous decrease in ATP and lactate levels in hepatocellular carcinoma cells." (PMID 39695152, 2024). "This interaction mechanism plays a crucial role in regulating SLC50A1 expression in liver cancer cells and may contribute to the pathogenesis of hepatocellular carcinoma." (PMID 39695152, 2024).
liver cancer (1 paper, 2024). An epithelial or non-epithelial malignant neoplasm that arises from the liver. "This analysis revealed a significant increase in relative m6A levels within the SLC50A1 3’ UTR in liver cancer cells." (PMID 39695152, 2024). "Overexpression of SLC50A1 predicts unfavorable prognosis in liver cancer patients, a finding that was supported by our analysis of clinical tissues." (PMID 39695152, 2024). "The results indicated a remarkable overexpression of SLC50A1 in liver cancer cell clusters." (PMID 39695152, 2024). "Hence, our study identifies the METTL3/SLC50A1 axis as a novel relevant therapeutic target in the context of liver cancer." (PMID 39695152, 2024). "In conclusion, these results suggest that SLC50A1 modulates HCC proliferation by impacting the glycolytic pathway, and that 2-DG effectively inhibits liver cancer cell proliferation both in vitro and in vivo." (PMID 39695152, 2024). "In this study, we identified through GEO and TCGA databases that SLC50A1 is significantly upregulated in liver cancer compared to normal tissues." (PMID 39695152, 2024).
schizophrenia (1 paper, 2018). A major psychotic disorder characterized by abnormalities in the perception or expression of reality. "Nonetheless, a subset of PD (e.g., SLC50A1), ALS (ITPR2), and schizophrenia (RENBP) susceptibility genes were part of the microglia signature in the aged human brain." (PMID 29416036, 2018).
tumor (3 papers, 2024 to 2025). "Additionally, transporters such as SLC50A1 (SWEET1) have emerged as promising diagnostic biomarkers due to their strong association with tumor grade and prognosis." (PMID 41458541, 2025). "Consistently, we found that SLC50A1 was significantly more expressed in tumor tissues than in normal tissues." (PMID 39695152, 2024). "The results indicated that knocking down SLC50A1 led to slower tumor growth and increased sensitivity to DOX, resulting in a reduced tumor growth rate." (PMID 39695152, 2024). "In vivo experiments similarly indicated that SLC50A1 expression affects tumor growth rates and DOX resistance, suggesting that SLC50A1 might facilitate DNA damage repair in DOX-treated HCC cells via the glycolytic pathway." (PMID 39695152, 2024). "Additionally, TUNEL staining showed that downregulation of SLC50A1 enhanced apoptosis in tumor tissues." (PMID 39695152, 2024). "We analyzed the expressions of SLC39A1, SLC50A1 and SLC66A3 across tumour stages from Stage I to Stage IV in the TCGA database." (PMID 40462487, 2025).
cancer (2 papers, 2022 to 2025). A tumor composed of atypical neoplastic, often pleomorphic cells that invade other tissues. "In detail, SLC50A1 and SYT1 were significantly upregulated in all cancers compared to healthy bladder tissue." (PMID 36352089, 2022). "SLC50A1 and SYT1 were significantly upregulated in all cancers compared to healthy bladder tissue." (PMID 36352089, 2022).
SLC50A1 also shares sentences with these, for which no sentence is quoted: breast carcinoma (2 papers); prostate carcinoma (1).